TNF (tumor necrosis factor)
Diseases named in the same sentence as TNF in open-access papers (continued):
Sharing a sentence is not in itself a finding about the gene and the disease.
Sepsis (continued). "Accumulating evidence demonstrates that the inhibition or specific antagonism of MCP-1 results in decreased release of TNF-α, IL-1β and IL-6 by macrophages and confers survival benefits on mice following sepsis." (PMID 28472164, 2017). "By flow cytometric analysis, they showed that the intracellular levels of IL-6 and TNF-α in patients with sepsis were significantly lower than those of healthy control subjects." (PMID 28274246, 2017). "As pro-inflammatory cytokines, serum and plasma TNF-α and IL-6 levels have been shown to increase significantly among patients with sepsis, particularly in those who are culture-positive." (PMID 29073262, 2017). "In agreement with the ex vivo TNFα stimulation assay and the endotoxin levels in sepsis patients, we found an almost identical optimal LPS concentration of 500 pg/mL after 3 hours for both patient groups." (PMID 29387728, 2017). "Another observation comparing 20 patients after hernia repair or cholecystectomy with 15 sepsis patients showed increased TNFα in the post-surgical group compared to sepsis patients." (PMID 28771573, 2017). "In the early response of sepsis, both IL-6 and TNF-α are major pro-inflammatory cytokines and are involved in physiological dysfunction." (PMID 28661460, 2017). "Third, due to the complex interactions of pro- and anti-inflammatory mediators, it is most likely that the relationship between ET-1, TNF-α and liver dysfunction is only one possible pathway for the development of liver failure in sepsis." (PMID 28542386, 2017). "Functional studies that take into account genetic and environmental factors should investigate how the TNF-α −308 A/G polymorphism affects TNF-α production and the cytokine’s role in pathogenesis of sepsis." (PMID 29212277, 2017). "It has been proven in vivo that glabridin can protect hygromycin-resistant BDF1 transgenic mice against LPS-induced sepsis by reducing the production of various inflammatory mediators such as TNF-α and NO." (PMID 28039487, 2017). "In contrast, when someone is acutely ill from sepsis the TNF that made them ill has largely come and gone, having set in train many harmful pathways." (PMID 28451786, 2017). "The level of TNF-α and IL-1β in sepsis group was markedly higher than the sham group in both 24 and 96 h post LPS injection." (PMID 28250969, 2017). "Our data showed that pro-inflammatory cytokines, such as TNF-α and IL-8 were significantly increased in the sepsis-non AKI compared with the healthy controls." (PMID 28296904, 2017). "Various inflammation-associated factors, including LPS, TNF-α, IL-1, nitric monoxide, PAF, Braun’s lipoprotein (BLP), and high-mobility group box 1 protein, promote inflammation leading to sepsis." (PMID 28912777, 2017). "Our study is the first to demonstrate that GIK decreased the rate of mortality in a rat model of sepsis, decreased the production of intestinal tissue proinflammatory cytokines, including IL-1β, IL-6 and TNF-α, and increased the level of IL-10." (PMID 28428961, 2017). "IL-6 and TNF-α were significantly increased in the sepsis group compared with the sham group, and this increase was reduced in the sepsis group treated with MSCs." (PMID 29273091, 2017). "Severity of sepsis and risk of death is supported by a dysregulated host cytokine response with progressively increasing IL10/TNF ratio." (PMID 31058274, 2017). "Our ex vivo results of reduced TNFα levels in sepsis are in accordance with previous clinical studies." (PMID 28771573, 2017). "Compared to the NC group, protein concentrations of CXCL-12, MMP-9, VEGF, TNF-α, and NO were significantly higher in the sepsis groups." (PMID 28513569, 2017). "FC-99 protected mice in the CLP-induced polymicrobial sepsis model and significantly decreased the serum levels of TNF-α and IL-6." (PMID 28976923, 2017). "We conducted a wound-healing assay with healthy and sepsis sera containing different concentrations of TNF-α or EGF or EGF receptor inhibitor cetuximab." (PMID 28086962, 2017).
Sepsis (continued). "The results presented here provide a rationale to test the effects of TLR4 and TNF-α antagonists on LPS-induced muscle wasting in sepsis or metabolic endotoxemia patients." (PMID 28742154, 2017). "In order to study the underlying mechanisms, we then tested the excessive release of Angpt-2 from ECs upon stimulation with various sepsis mediators (i.e. IL-1ß, TNFα, LPS, IFNγ)." (PMID 28276491, 2017). "Elevated levels of cytokines, such as IL-1β, TNF-α, and IL-6, have been observed in the brain parenchyma and cerebrospinal fluid after sepsis." (PMID 28236057, 2017). "Consistently, the pre-degranulation of mast cells by compound 48/80 in models of lethal sepsis resulted in a significant decrease in the serum levels of TNF-α and interleukin-8 (IL-8)." (PMID 28388962, 2017). "All concentrations of TNF-α improved cell migration in wounds, both those cultured in healthy and sepsis sera (P < 0.01 in all concentrations)." (PMID 28086962, 2017). "We were unable to demonstrate significant differences in baseline TNFα levels between controls, patients with post-surgical inflammation or sepsis." (PMID 28771573, 2017). "The sepsis patients exhibited significantly higher plasma concentrations of TNF-α, IL-6 and IL-1β compared with the healthy controls." (PMID 28472164, 2017). "Here, we demonstrate that IL-1β production during sepsis with uropathogenic E. coli is mediated by caspase-8, since caspase-8 and RIPK3 double knock out mice show substantially lower cytokine during sepsis and increased survival after injection of TNFα." (PMID 28428949, 2017). "TNF-α is the primary inflammatory mediator in sepsis as it regulates other downstream cytokines such as IL-6 and IL-10." (PMID 28086962, 2017). "In clinical practice, the IL-10: TNF-α ratio is one recommended biomarker used to monitor the progression of sepsis." (PMID 27556404, 2016). "We found that the TNF release induced by BCG or CB extracts was decreased in PBMCs from patients with severe sepsis." (PMID 27441846, 2016). "In a murine CLP model of polymicrobial sepsis, IL-17A from γδT cells was detected, but its depletion led to a decrease in bacteremia and reductions in systemic proinflammatory cytokines (TNF-α, IL-1β, and IL-6) and chemokines." (PMID 27334720, 2016). "Sepsis-induced production and release of pro-inflammatory TNFα by isolated splenocytes, cultured and stimulated for 24h with LPS, was measured five days post CLP." (PMID 27574993, 2016). "Following CLP-induced sepsis, we detected a significant rise in the serum levels of proinflammatory cytokines such as IL-6 and TNF-α, as well as a simultaneous increase in the serum levels of the anti-inflammatory IL-10." (PMID 27044016, 2016). "Pentoxifylline, a xanthine-derived phosphodiesterase inhibitor that decreases TNF-α and IL-6 production, has been reported to improve the clinical outcome of preterm sepsis." (PMID 28066425, 2016). "Another limitation is inability to use other inflammatory markers as IL-6 and TNF-alpha besides CRP in comparison to PSP for early sepsis diagnosis." (PMID 27689072, 2016). "In sepsis, cytokines like TNF-α, interleukin-1 beta (IL-1β) and IL-6 which are released after infection, play an important role in the inflammatory process." (PMID 27150961, 2016). "Blocking TNF-α production is thought to be crucial for improving cell survival in cecal ligation puncture sepsis and intra‐abdominal sepsis, because TNF-α facilitates the induction of cell injury via the activation of caspase/p38 and JNK MAP kinase cascades." (PMID 27472555, 2016). "LPS can promote overexpression of proinflammatory cytokines including IL-6, IL-1β, and TNF-α, which was involved in subsequent sepsis." (PMID 28042205, 2016). "In this scenario, miRNA at the same time regulate the expression of sepsis related genes, such as IL-6 and TNF, and are regulated in their own expression by these factors, highlighting the deep integration of miRNAs in the pathophysiology of septic disease." (PMID 26761003, 2016).
Sepsis (continued). "Evidence exists that excessive production of the cytokines TNF-α and IL-1 significantly contributes to the development of multiple organ damage in endotoxemia and sepsis in humans, in the equine endometritis, equine asthma and colic." (PMID 27316332, 2016). "Among the cytokines involved in sepsis, TNF-α, a primary mediator of septic shock, is secreted immediately after infection and triggers the pathological process of septic shock." (PMID 27716835, 2016). "Although clinical studies have led to the development of new therapeutic approaches against severe inflammation and sepsis, the major focus has been on decreasing the cytokine storm, especially tumor necrosis factor (TNF)-α production." (PMID 27472555, 2016). "Pro-inflammatory cytokines like TNF-α, IL-1β, and IL-6 are responsible for severe manifestations in sepsis and septic shock." (PMID 27430881, 2016). "Acutely, sepsis increased TNF‐α and IL‐6 mRNA in muscle, and the increase in TNF‐α was significantly greater in ZM mice." (PMID 27811170, 2016). "Apart from TNF, miRNAs were shown to play a functional role in the regulation of sepsis by targeting the toll-like receptor (TLR)/NF-κB signalling pathways." (PMID 26761003, 2016). "Another investigation found that a blockade of the α2A-adrenoceptor with BRL-44408 suppresses early pro-inflammatory mediators (TNF-α, IL-6, etc.)and, thus, improves liver dysfunction during sepsis." (PMID 27347929, 2016). "And some reports indicated that NF-κb pathway was activated during sepsis and increased expression of proinflammatory cytokines such as IL-6, IL-1β, and TNF-α, leading to excessive inflammation response." (PMID 28042205, 2016). "During infection and sepsis elevated levels of pro-inflammatory cytokines, e.g. TNF-α and IFN- γ have been reported." (PMID 27932936, 2016). "Mild ZD, established by a 66% reduction in the dietary Zn intake, exacerbated the sepsis‐induced increase in skeletal muscle TNF‐α mRNA content at 24 h suggesting early amplification of local muscle‐specific inflammation responses in the septic state." (PMID 27811170, 2016). "The inflammatory cytokines IL-6, IL-1β, and TNF-α have been well documented to increase mortality in sepsis." (PMID 27009867, 2016). "The RGD sensitive nature of WISP1 mediated lung injury in CLP10 encouraged us to pursue a role for integrins in the pro-inflammatory state of the lungs in sepsis and thus we focused on cell culture models of TNF-α release from macrophages." (PMID 27349568, 2016). "TNF-α is the first cytokine in the blood circulation in human sepsis and promotes leukocytes recruitment to the inflammatory focus." (PMID 27630733, 2016). "Patients with sepsis exhibit high level of circulating pro-inflammatory cytokines such as tumor necrosis factor (TNFα) or Interleukin-6 and IL-6 seems to correlate strongly with decreased survival in septic patients." (PMID 27574993, 2016). "Patients with sepsis had a reduced capacity to release TNF-α and IL-1β upon LPS stimulation compared to healthy controls." (PMID 27737683, 2016). "Hypercytokinemia occurs in response to sepsis (including viral pneumonias) resulting in an abnormally increase of primary proinflammatory cytokines of blood serum, tumor necrosis factor alpha and interleukin-1 (IL-1)." (PMID 28096614, 2016). "E/S induced anti-sepsis protection mainly mediated by inhibition of inflammatory cells infiltration, down-regulation of TNF-alpha, IL-8 and lactic dehydrogenase (LDH), and inhibition of NF-κB and p38 pathways in mice 24 h post-CLP." (PMID 28119611, 2016). "Naringin protected mice from CLP-induced sepsis in an HO-1-dependent manner by reducing serum TNF-α and HMGB1 levels." (PMID 27716835, 2016). "Sequentially, the up-regulated NFκB-MAP kinases, over-produced TNF-α and iNOS-derived NO (nitrite) involved in the development of severe sepsis and septic shock." (PMID 27861595, 2016).
Sepsis (continued). "In this study, we only measured serum TNF-α levels (at 1 h) as the representative cytokine for the early stage of sepsis and HMGB1 levels (at 24 h) for the late stage." (PMID 27716835, 2016). "In most of our experiments, we made use of the endotoxemia model, but we observed increased EV production and similar changes in CPE and CSF miRNA levels in the CLP mouse model of sepsis, and upon systemic injection of the pro‐inflammatory cytokine TNF." (PMID 27596437, 2016). "In the early stages of sepsis, the production of NO was decreased and the release of TNF-α, IL-6, and IL-1β was inhibited by citrulline supplementation." (PMID 27195281, 2016). "During the early stages of sepsis, the body is at a proinflammatory stage accompanied by the release of a large number of proinflammatory cytokines such as TNF-α, IL-1β, and IL-6." (PMID 27195281, 2016). "The combination of anti-TNF-α drugs and antibiotic alleviates the outcome of S. aureus arthritis and sepsis in a mouse model." (PMID 27446000, 2016). "TNF is an inflammatory marker released by activated macrophages, monocytes, and neutrophils, and has been shown to have a major role in both sepsis and septic AKI." (PMID 27372077, 2016). "Our model of sepsis displays early and massive inflammation as TNFα and IL-6 rise significantly (60-fold higher concentration as compared to Sham for both these cytokines at the second hour post CLP)." (PMID 27574993, 2016). "Plasma samples from sepsis patients, in contrast, induced variable levels of endothelial activation despite their comparable levels of IL-6 and TNF-α." (PMID 27503310, 2016). "In variant TLR4+896 allele carriers with severe sepsis, a significantly positive correlation was noted between LPS-stimulated TLR4 expression and corresponding TNFα/nitrite production." (PMID 27861595, 2016). "The up-regulated TLR4 expression-increased TNFα/iNOS/nitrite levels and subsequently systemic acute inflammatory status (high plasma sCD14 and total NO levels) resulted in severe sepsis among them." (PMID 27861595, 2016). "Increased systemic and local levels of IL-1 β and IL-6, together with tumor necrosis factor alpha, are known to correlate with a more severe development of sepsis in mice." (PMID 27527222, 2016). "Regarding TNFα, IL-6, IL-10, sTNFr, our results confirm that both pro-inflammatory and anti- inflammatory responses occur early and simultaneously in human sepsis as well as after mild CLP procedure in mice." (PMID 27574993, 2016). "Sepsis is a serious clinical syndrome, which is mediated by an early (such as TNF-α and IL-1) and late (such as HMGB1) pro-inflammatory cytokine response to infection." (PMID 27980458, 2016). "In TNF-α induced mouse systematic sepsis model, RIP3-KO mice recovered from hypothermia and survived longer, which was partly by reducing DAMPs and IL-1β, IL-6." (PMID 27195494, 2016). "In supernatant on cultured CD16+ monocytes of variant TLR4+896A/G allele carriers and severe sepsis cases, significantly higher baseline and LPS-stimulated TLR4 over-expression was accompanied by TNFα and nitrite over-production." (PMID 27861595, 2016). "The levels of TNF-α, a key cytokine, are known to be elevated during many inflammatory conditions, including experimental sepsis." (PMID 27064683, 2016). "Here we show that methane-rich saline (MS) ip treatment (16 ml/kg) alleviated endotoxin shock, bacteria-induced sepsis and dextran-sulfate-sodium-induced colitis in mice via decreased production of TNF-α and IL-6." (PMID 27405597, 2016). "Plasma levels of TNF-α, IL-6, and IL-10 were strongly increased after 3 and 6 hours from LPS administration, as well as after sepsis induction in the CLP model, in comparison to those measured in saline-injected or sham-operated mice." (PMID 26963510, 2016). "The dynamic of TNF-α during the sepsis process of the neonates was similar to that of INF-γ and depended on the time of sepsis and the gestational age of the infant." (PMID 27293317, 2016).
Sepsis (continued). "Since the essence of sepsis is the inflammatory reactions, we detected the productions of inflammatory cytokines, such as TNF-α, IL-1β, and IL-6, in kidney tissue by ELISA." (PMID 26904148, 2016). "It was observed that blood urea nitrogen (BUN) and tumor necrosis factor alpha (TNF-α) levels were dramatically increased in the CLP induced sepsis group (43.88 ± 1.905 mg/dl, 37.63 ± 1.92, respectively) when compared to the sham group." (PMID 27150961, 2016). "Blocking Ab against TNF-α provided weak prophylactic and poor therapeutic effects in large cohorts of patients with sepsis." (PMID 26757701, 2016). "This suggested that citrulline supplementation reduced the release of TNF-α, IL-6, and IL-1β in the early stages of sepsis." (PMID 27195281, 2016). "Some cytokines such as circulating TNF have been correlated with the prognosis of severe sepsis and such findings have served as a basis for immunotherapy of sepsis targeting TNF." (PMID 27441846, 2016). "The protective effect was further elaborated by a murine sepsis model in which an apigenin-rich diet considerably reduced the expression of miR-155 and TNF-α in the lungs." (PMID 27890015, 2016). "Citrulline supplementation reduced the release of TNF-α, IL-6, and IL-1β in the early stages of sepsis." (PMID 27195281, 2016). "There is no study demonstrating the effect of EGFR on the production of myocardial TNF-α in endotoxemia or sepsis." (PMID 26486084, 2015). "TNF-α is widely accepted as the initial mediators in the pathogenesis of sepsis; it plays a key role in endogenous inflammation to induce IL-1β and IL-6 production during the early phase of CLP." (PMID 26273145, 2015). "In summary, sepsis leads to TNF‐dependent suppression of T cell proliferation in vivo involving induction of Treg cells." (PMID 26734459, 2015). "The BBB failure in sepsis is explained by endothelial cell injury through cytokines such as TNF-α and IL-β that leads to upregulation of endothelial surface antigens and subsequent white blood cells adherence as well as microcirculatory dysfunction." (PMID 26228515, 2015). "TNF-α plays a key role in CLP-induced sepsis; therefore we evaluated the expression of this proinflammatory cytokine 18 hours after the CLP procedure." (PMID 25873765, 2015). "This gave fair warning that such antibody was likely to be impractical for treating acute inflammatory disease once it is underway, and so it proved when etanercept, a major commercial anti-TNF biological agent, was first tested in sepsis patients." (PMID 26221543, 2015). "The antipathogen function of TNF, together with the large dose employed by present-day standards, plausibly explains outcomes being worse than controls in some sepsis groups." (PMID 26221543, 2015). "We found high circulating plasma cytokine levels, which in comparison to their baselines values showed peaks immediately after sepsis/VILI induction (TNF-α) or three hours following induction (IL-6)." (PMID 25879802, 2015). "A recent study on sepsis patients compared plasma levels of TNF-α, IL-6 and IL-10 to immune-staining of freely circulating monocytes and leukocytes." (PMID 25958003, 2015). "EGFR can activate downstream PI3K/AKT and MAPK for cell proliferation and MAPK is the most important signal molecular regulating the generation of TNF-α in endotoxemia or sepsis." (PMID 26486084, 2015). "Previous studies have shown that TNFα and interleukin 1β contribute to myocardial dysfunction in sepsis." (PMID 26640720, 2015). "Excessive release of proinflammatory mediators which are induced by endotoxin like tumor necrosis factor-alpha (TNF-alpha) and reactive oxygen species (ROS) causes systemic inflammatory response during sepsis." (PMID 25948886, 2015). "All these results provided a new insight of how EGFR regulation the production of TNF-α in cardiomyocytes and a potential new target for the treatment of cardiac dysfunction in sepsis." (PMID 26486084, 2015).